DNAH10OS (dynein axonemal heavy chain 10 opposite strand)
Synonyms: FLJ45278
Gene: Long non-coding RNA gene on chromosome 12 (123,925,461 to 123,934,984, reverse strand). Ensembl gene ENSG00000250091.
Diseases named in the same sentence as DNAH10OS in open-access papers:
DNAH10OS is named in the same sentence as 3 diseases in open-access papers, as found by Europe PMC text mining. Sharing a sentence is not in itself a finding about the gene and the disease. The quoted sentences say what the papers report.
glioblastoma (1 paper, 2020). The most malignant astrocytic tumor (WHO grade IV). "Kaplan-Meier curves and ROC curves suggested that the risk scoring model based on the 6 lncRNAs (CPB2-AS1, AC092171.2, LINC00665 and LINC00460, PRRT3-AS1, and DNAH10OS) had a strong predictive ability for glioblastoma patients." (PMID 32851059, 2020).
type 2 diabetes (1 paper, 2023). "Besides, genetically elevated expression of CCNE2 on 8q22.1, HAUS6 on 9p22.1, CWF19L1 on 10q24.31, CCDC92 on 12q24.31 and DNAH10OS on 12q24.31 showed protective effects on type 2 diabetes risk." (PMID 37540242, 2023).
cancer (1 paper, 2022). A tumor composed of atypical neoplastic, often pleomorphic cells that invade other tissues. "However, the rest in the model, namely, AC015819.1, AC090198.1, DNAH10OS, and AL358472.3, were reported for the first time in cancer, which suggests that a large number of lncRNAs have not been discovered yet and that lncRNAs have great potential as prognostic biomarkers for BRCA." (PMID 36591508, 2022).